SDHAP2 (SDHA pseudogene 2)
Synonyms: formerly SDHAL2; SDHALP2
Gene: Transcribed unprocessed pseudogene on chromosome 3 (195,658,096 to 195,685,904, forward strand). Ensembl gene ENSG00000215837.
Diseases named in the same sentence as SDHAP2 in open-access papers:
SDHAP2 is named in the same sentence as 3 diseases in open-access papers, as found by Europe PMC text mining. Sharing a sentence is not in itself a finding about the gene and the disease.
SDHAP2 shares sentences with these, for which no sentence is quoted: paraganglioma (1 paper); pheochromocytoma (1); psoriasis (1).